CANX (calnexin)
Description:
Calcium-binding protein that interacts with newly synthesized monoglucosylated glycoproteins in the endoplasmic reticulum. It may act in assisting protein assembly and/or in the retention within the ER of unassembled protein subunits. It seems to play a major role in the quality control apparatus of the ER by the retention of incorrectly folded proteins. Associated with partial T-cell antigen receptor complexes that escape the ER of immature thymocytes, it may function as a signaling complex regulating thymocyte maturation. Additionally it may play a role in receptor-mediated endocytosis at the synapse.
Synonyms: CNX; IP90; P90
Tractability: Antibody: UniProt predicts a signal peptide or a membrane-spanning region. PROTAC: UniProt records ubiquitination sites on it; ubiquitination databases record sites on it; its protein half-life has been measured.
Target class: Other cytosolic protein
Gene: Protein-coding gene on chromosome 5 (179,678,628 to 179,731,641, forward strand). Ensembl gene ENSG00000127022.
Subcellular location: Endoplasmic reticulum membrane; Mitochondrion membrane; Melanosome membrane
Subcellular location (Human Protein Atlas): Endoplasmic reticulum
Pathways (Reactome):
Immune System: Antigen Presentation: Folding, assembly and peptide loading of class I MHC; Interleukin-27 signaling; Interleukin-35 Signalling; MHC class II antigen presentation
Disease: Assembly of Viral Components at the Budding Site; Maturation of DENV proteins; Maturation of spike protein
Cell-Cell communication: Regulation of CDH1 posttranslational processing and trafficking to plasma membrane
Metabolism of proteins: Calnexin/calreticulin cycle
Gene Ontology:
Molecular function: protein binding; RNA binding; calcium ion binding; protein folding chaperone
Biological process: clathrin-dependent endocytosis; ERAD pathway; protein folding; protein folding in endoplasmic reticulum; protein secretion; synaptic vesicle endocytosis; viral protein processing
Cellular component: endoplasmic reticulum; endoplasmic reticulum membrane; extracellular exosome; melanosome membrane; membrane; mitochondria-associated endoplasmic reticulum membrane contact site; endoplasmic reticulum lumen; lumenal side of endoplasmic reticulum membrane; mitochondrial membrane; endoplasmic reticulum quality control compartment; nuclear membrane; presynapse
Genetic constraint (gnomAD): Loss-of-function variants: 4 observed, 34.15 expected, observed/expected ratio (o/e) 0.12, 90% interval 0.057 to 0.27. The upper end of that interval is the gene's LOEUF score, 0.27, which puts it in group 1 of 6, group 1 being the genes least tolerant of losing a copy. Missense variants: 294 observed, 372.66 expected, observed/expected ratio (o/e) 0.79, 90% interval 0.72 to 0.87. Synonymous variants: 124 observed, 122.86 expected, observed/expected ratio (o/e) 1.01, 90% interval 0.87 to 1.17.
Homologues: Orthologues: chimpanzee CANX (99% identical), macaque CANX (99% identical), pig CANX (96% identical), dog CANX (95% identical), rabbit CANX (95% identical), rat Canx (94% identical), mouse Canx (93% identical), guinea pig CANX (93% identical), tropical clawed frog canx (80% identical), zebrafish canx (71% identical), Drosophila melanogaster Cnx99A (49% identical), Drosophila melanogaster CG1924 (43% identical), and 1 more. Paralogues in human: CLGN (58% identical), CALR (30% identical), CALR3 (21% identical).
Diseases named in the same sentence as CANX in open-access papers:
CANX is named in the same sentence as 111 diseases in open-access papers, as found by Europe PMC text mining. Sharing a sentence is not in itself a finding about the gene and the disease. The quoted sentences say what the papers report.
breast carcinoma (14 papers, 2013 to 2025). "We next explored if high Tn levels were linked to ER O-glycosylation, as in the case of breast carcinomas and indeed found that Tn staining co-localised extensively with the ER marker calnexin in the carcinoma samples." (PMID 24618899, 2014). "Additionally, low or defective expression of calnexin in primary breast cancer was reported to be associated with a higher risk of brain metastases, due to defects in T-cell-based immunosurveillance." (PMID 34885011, 2021). "In addition, high expression of FNDC1 (probe 226930_at, p = 0.019) and the low expression of PDIA3 (probe 227033_at, p = 0.0037), HSPA5 (probe 230031_at, p = 0.0024) and CANX (probe 238034_at, p = 0.0013) were also associated with a worse overall survival in breast cancer patients." (PMID 34885011, 2021). "In a breast cancer cell line, pomiferin increases the expression of apoptotic genes CANX and BCAP31, though the effect is modest." (PMID 40332068, 2025). "Youden index analysis also showed that five proteins including S100A9, SRSF6, THBS1, CUL4A, and CANX can accurately diagnose breast cancer patients at the metastatic and primary stages from healthy individuals." (PMID 32793473, 2020). "The identified PBMC biomarkers (TMSB4X, HSPA4, S100A9, SRSF6, THBS1, CUL4A, and CANX) were significantly upregulated in the breast cancer patients at the metastatic stage compared to both the primary stage and healthy individuals (p < 0.001)." (PMID 32793473, 2020). "To investigate it, we next analyzed the colocalization of OTUD3 and GRP78 or PTEN in lung and breast cancer cell lines using immunofluorescence and used Calnexin as a ER marker." (PMID 31266968, 2019). "Finally, an independent validation showed FNDC1, A1BG, PDIA3, HSPA5, and calnexin as significant prognostic markers for human breast cancer patients." (PMID 34885011, 2021). "Finally, in silico analysis confirmed that a gene set consisting of S100A9, SRSF6, THBS1, CUL4A, and CANX were found to provide an insight for the identification of metastasis in breast cancer patients." (PMID 32793473, 2020). "In other words, although CANX could be considered as a suitable diagnostic PBMC marker, its prognostic effect depends on the subtype of breast cancer." (PMID 32793473, 2020). "Increased de novo FA biosynthesis and FASN upregulation has also been observed in breast cancer, melanoma, and hepatocellular carcinoma, and de novo FA biosynthesis and lipogenesis has been shown to be essential for protein palmitoylation of Ras, Wnt, calnexin, and Src in proliferating cells." (PMID 34606827, 2021). "Accordingly, in our study, the low gene expression of calnexin, HSPA5, and PDIA3 had a significant prognostic value for OS and DMFS in human breast cancer patients." (PMID 34885011, 2021). "By analyzing heterogeneous intratumor subpopulations and metastatic sites, we demonstrated that FNDC1, A1BG, CANX, HSPA5, and PDIA3 may be key factors to tumor malignancy in a canine model of breast cancer." (PMID 34885011, 2021). "Finally, a gene set consisting of S100A9, SRSF6, THBS1, CUL4A, and CANX were introduced as potential candidate genes helpful in distinguishing metastatic from non-metastatic breast cancer patients." (PMID 32793473, 2020). "The results of a recent study indicate that low or defective expression of APM components β2-microglobulin, antigen processing-1 and calnexin, as well as paucity of CD8+ T cell infiltration in the primary breast cancers, may dictate high risks of developing brain metastasis." (PMID 23340652, 2013). "We further characterised ultracentrifuged EVs from the different breast cancer cells by Western blot analysis, which confirmed the expression of the tetraspanin CD9 but not of calnexin, which are markers of EVs and the endoplasmic reticulum, respectively." (PMID 40524202, 2025).
breast carcinoma (continued). "In addition, EpCAM- and AnxA2-positive exosomes are negative for the expression of calnexin and GM130, respectively, and show the purity of exosomes isolated from breast cancer serum samples." (PMID 31992335, 2020).
melanoma (12 papers, 1999 to 2024). A malignant, usually aggressive tumor composed of atypical, neoplastic melanocytes. "CANX (calnexin) has been associated in melanoma with an enhancement in the expression of PD-1 on CD4+ and CD8+ T cells, but also with a promotion of tumor growth and an inhibition of T cell infiltration." (PMID 37686682, 2023). "In melanoma models, CANX knockout enhanced the infiltration and effector functions of T cells in the tumor microenvironment and inhibited tumor growth." (PMID 34476221, 2021). "Interestingly, HLA-class I APM component levels (Delta, LMP-7/10, TAP-1, Calnexin, Tapasin, β2-microglobulin, and HLA-A,B,C) were lower in immature epidermal LCs compared to melanoma-positive SLN LCs, and significantly increased after LCs maturation." (PMID 38791968, 2024). "Moreover, plasma membrane localization of calnexin has been detected in cancerous tumors such as oral squamous cell carcinoma and melanoma while another study reported calnexin as being secreted in the serum of lung cancer patients, making calnexin a possible sero-diagnostic marker." (PMID 36766745, 2023). "Interestingly, calnexin has been shown to be downregulated in brain metastases of breast tumors compared to unpaired primary breast lesions as well as in metastatic melanoma lesions in comparison to primary melanoma lesions." (PMID 26334999, 2015). "We found that ER proteins IRE1α, Atf6, Calnexin, and CHOP are all equally expressed in resistant melanoma cells." (PMID 34282258, 2021). "In contrast, the ER marker, calnexin, was enriched in the melanoma lysate and absent in the iEV fraction, thus confirming the presence of exosomes in the polydisperse zebrafish iEVs population isolated with the NBI method." (PMID 35628321, 2022). "In addition, the expression ER chaperones GRP78, GRP94, CALR, calnexin and PDI was dose- and time-dependently up-regulated after exposure to 11-dehydrosinulariolide in melanoma cells." (PMID 23015779, 2012). "Hence, it is proposed that the up-regulations of the ER chaperones calnexin, CALR and PDI after exposure to 11-dehydrosinulariolide are likely self-rescuing responses of the tumor cells or the onset of ER stress-mediated apoptosis induced by the treatment in the melanoma cells." (PMID 23015779, 2012).
viral infection (10 papers, 2016 to 2024). "Other upregulated ER-stress proteins including calreticulin and calnexin important for calcium storage and protein folding were shown to act crucial role in viral infections." (PMID 31751365, 2019). "Calnexin is an ER-residing chaperone protein and serves as a marker protein of ER, which is essential for controlling the production of glycosylated proteins in the process of viral infection and immune escape." (PMID 36238596, 2022). "Interestingly, KDEL receptors as well as the chaperones GRP78, calreticulin, and calnexin are up-regulated by cells under stress conditions and viral infections as part of the stress response." (PMID 30621148, 2019). "ER chaperones are important molecules involved in the ERS, among which two critical chaperone systems, calnexin/calreticulin, and GRP78/GRP94, have been widely studied for their roles in viral infection." (PMID 35562870, 2022). "A calnexin transcript was upregulated in the Ixodes ricinus-derived cell line IRE/CTVM19 at day 2 post-infection with the flavivirus tick-borne encephalitis virus (TBEV), which may have an important role in the response of tick cells to virus infection." (PMID 32039052, 2019). "The results showed that EDEM1 gene, calreticulin, and calnexin mRNA levels were all not modified in cp BVDV-infected MDBK cells, indicating that viral infection did not activate the ATF6 and XBP1 signaling pathways." (PMID 36939351, 2023). "However, upon virus infection, the majority of GRP78/BiP was found in the lighter fractions (fractions 2–4), whereas viral nonstructural proteins 2C and 3A strongly cosedimented with calnexin (fractions 6–8)." (PMID 27004760, 2016).
colorectal cancer (9 papers, 2007 to 2025). A primary or metastatic malignant neoplasm that affects the colon or rectum. "Conversely, increased CANX expression was associated with poor clinical outcomes in colorectal cancer patients." (PMID 34914716, 2021). "In colorectal cancer, miR-148a-3p is eminently capable of repressing the expression of calnexin (CANX) and B2M/MHC-I, thereby decidedly restricting the anti-cancer efficacy of CTLs." (PMID 40191187, 2025). "In conclusion, we have used AGO-qCLASH to dissect the TSS-miRNA targetome in HCT116 colorectal cancer cells and discovered that miR-320a targets CANX and stimulates the UPR." (PMID 34914716, 2021). "Consistent with previous reports, we establish that miR-320a is repressed in colorectal cancer while CANX is up-regulated." (PMID 34914716, 2021). "In colorectal cancer, overexpression of CANX predicted poor prognosis of the patients, and its knockdown attenuated aggressive phenotypes of cancer cells." (PMID 31795200, 2019). "To determine a role for calnexin in colorectal cancer cell survival and 5FU-induced cell death, we silenced calnexin gene expression in HCT116 cells using siRNA-mediated gene silencing." (PMID 27369741, 2016). "The significant findings of this study identify the ER calcium binding chaperone calnexin as promising prognostic marker and therapeutic target in colorectal cancer." (PMID 27369741, 2016). "We have discovered novel mutations in the antigen presenting machinery genes; Tapasin, Erp57, Calreticulin and Calnexin in colorectal cancer." (PMID 17316446, 2007). "CANX is a prognostic marker and potential therapeutic target in colorectal cancer." (PMID 34476221, 2021). "In order to examine the potential role of ER stress in colorectal cancer we determined the expression of the ER stress proteins calreticulin, calnexin, GRP78 and GRP94 in colorectal tumour and matched normal tissue from patients with Stage II (n = 8) and Stage III (n = 15) disease." (PMID 27369741, 2016). "In summary, this study indicates that the calnexin protein levels may represent a new indicator of poor clinical outcome of stage II/III colorectal cancer patients who received 5FU-based chemotherapy." (PMID 27369741, 2016). "Furthermore, we establish the importance of calnexin in colorectal cancer cell survival and responsiveness to 5FU-based chemotherapy." (PMID 27369741, 2016). "Together, these results suggest a possible role for the calcium binding chaperone calnexin as a prognostic biomarker in stage 2 and 3 colorectal cancer and as a potential therapeutic target, which requires further validation in clinical and pre-clinical studies." (PMID 27369741, 2016). "Furthermore, our in vitro studies confirmed the importance of calnexin for colorectal cancer cell growth and proliferation and also demonstrated that calnexin deficiency could enhance responsiveness to 5FU-based-chemotherapy." (PMID 27369741, 2016). "Molecular chaperone calnexin and MHC-I expression can be suppressed by miR-148a-3p in colorectal cancer, attenuating tumor growth." (PMID 38041084, 2023). "In summary, we used qCLASH to identify the targetome of miR-320a in colorectal cancer cells and established that miR-320a regulates the ISR by targeting CANX." (PMID 34914716, 2021).
lung cancer (8 papers, 2019 to 2024). A malignant neoplasm involving the lung. "Another study showed that serum levels of CANX were significantly higher in patients with lung cancer, and its expression was a useful sero-diagnostic marker of the patients." (PMID 31795200, 2019). "Diagnostic serum markers are also in high demand for the early detection of lung cancer, and two strong biomarker candidates, cytoskeleton-associated protein 4 (CKAP4) and calnexin (CANX), have been identified using RPPAs." (PMID 39147028, 2024). "CLGN (increased 4.2-fold) is a functional analog of calnexin that is typically expressed in testes but is upregulated in malignancies, including gastric and non–small cell lung cancer." (PMID 37651191, 2023). "Specifically, we showed that lung cancer cells release exosomes with typical exosome markers, such as TSG101, CD81 and calnexin." (PMID 31664930, 2019). "Exosomes derived from lung cancer cells had typical exosome markers, such as CD81, TSG101 and calnexin, which fits with the previously reported protein content for exosomes." (PMID 31664930, 2019).
glioblastoma (6 papers, 2019 to 2025). The most malignant astrocytic tumor (WHO grade IV). "Consistent with our results, it was found that decreased expression of CANX was associated with favorable survival outcome and served as a biomarkers for tumor response in glioblastoma." (PMID 32351547, 2020). "Since CDKi induced endoplasmic reticulum (ER) stress in glioblastoma cells, characterized by increased calnexin abundance and cytochrome C redistribution, we investigated similar mechanisms in NB cells." (PMID 40753072, 2025). "In these glioblastoma cells, SPARC localized to the ER (co-stained with calnexin; Suppl." (PMID 31062076, 2019).
colon cancer (5 papers, 2010 to 2025). "In the present study, we significantly expand on the key role of calnexin in colon cancer cell survival by demonstrating that gene silencing of calnexin decreases clonogenic cell survival." (PMID 27369741, 2016). "BALB/c mice implanted with CT26 colon cancer cells expressing a codon-optimized Human Papilloma Virus 16 (HPV 16) E6 and E7 fusion protein (optE6E7) are protected through immunization with DCs transduced with LVs encoding optE6E7 and calnexin, a chaperone protein." (PMID 21106069, 2010). "We investigated the protein palmitoylation of two well-known S-palmitoylated proteins, calnexin and succinate dehydrogenase complex flavoprotein subunit A (SDHA), in human colon cancer cells (HCT-116) using two different detection methods." (PMID 39860245, 2025). "The data demonstrated that 10 nM bullatacin significantly upregulated the mRNA expression of calnexin and CHOP in two colon cancer cell lines." (PMID 34112202, 2021). "The expression levels of ER stress proteins calnexin, calreticulin, GRP78 and GRP94 were determined in n = 23 Stage II and III colon cancer fresh frozen tumour and matched normal tissue samples." (PMID 27369741, 2016). "Calnexin (Canx), a chaperone protein involved in the folding of MHC–I molecules, was markedly downregulated in Pirc colon tumors, and chronic SPI intake partially reversed this trend (dashed red box)—although not to the levels observed in WT normal AIN controls." (PMID 35159382, 2022).
diabetes (5 papers, 2014 to 2019). "MARCKS-PD overexpression in the neuroepithelium reversed the maternal diabetes-suppressed calnexin-MARCKS colocalization." (PMID 30655546, 2019). "Lindenmeyer and colleagues demonstrated that mRNA expression of GRP78/BiP, ORP150/HYOU1, S1P (MBTPS1), calnexin and XBP-1 increase in the kidneys of patients with established diabetes, compared with mild diabetes." (PMID 26239352, 2015).
neuroblastoma (5 papers, 2015 to 2022). Neuroblastoma (NB) is the most common solid, extracranial childhood tumor. "We additionally show that chronic thapsigargin treatment triggers an ectopic expression of CHOP that correlates with calnexin deficiency and ERO1α excess in SH-SY5Y neuroblastoma cells." (PMID 29170452, 2017). "We show an interaction between recombinantly-expressed GST-tagged Arc and endogenous calnexin in HEK293, SH-SY5Y neuroblastoma and PC12 cells." (PMID 28979192, 2017). "GST-Arc also bound calnexin from non-stimulated SH-SY5Y neuroblastoma cells, a neuronal cell line in which Arc protein is endogenously expressed (middle blot)." (PMID 28979192, 2017). "The ER marker calnexin was only detectable in total cell homogenates, whereas SOD2, the mitochondrial marker, could be detected in total cell homogenates as well as in the mitochondria fractions of mock-transfected as well as APPswedish transfected human neuroblastoma cells." (PMID 34440266, 2021).